SERPIND1 (serpin family D member 1)
Description:
Thrombin inhibitor activated by the glycosaminoglycans, heparin or dermatan sulfate. In the presence of the latter, HC-II becomes the predominant thrombin inhibitor in place of antithrombin III (AT-III). Also inhibits chymotrypsin, but in a glycosaminoglycan-independent manner. Peptides at the N-terminal of HC-II have chemotactic activity for both monocytes and neutrophils. [Isoform 2]: Shows negligible inhibition, in vitro, of thrombin and tPA and no inhibition of factor Xa, in vitro.
Synonyms: HC-II; HLS2; HCF2; HC2; D22S673; HCII; LS2; THPH10
Tractability: Small molecule: it has a binding pocket of medium quality. Antibody: its Gene Ontology location is reachable by antibodies, with high confidence; UniProt predicts a signal peptide or a membrane-spanning region. PROTAC: its protein half-life has been measured.
Gene: Protein-coding gene on chromosome 22 (20,774,112 to 20,787,721, forward strand). Ensembl gene ENSG00000099937.
Subcellular location (Human Protein Atlas): Vesicles; Predicted to be secreted
Pathways (Reactome):
Hemostasis: Amplification and propagation of coagulation cascade; Fibrin formation; Regulation of clotting cascade
Metabolism of proteins: Post-translational protein phosphorylation; Regulation of Insulin-like Growth Factor (IGF) transport and uptake by Insulin-like Growth Factor Binding Proteins (IGFBPs)
Gene Ontology:
Molecular function: protein binding; endopeptidase inhibitor activity; serine-type endopeptidase inhibitor activity
Biological process: blood coagulation
Cellular component: extracellular exosome; extracellular region; endoplasmic reticulum lumen
Genetic constraint (gnomAD): Loss-of-function variants: 34 observed, 36.72 expected, observed/expected ratio (o/e) 0.93, 90% interval 0.7 to 1.23. The upper end of that interval is the gene's LOEUF score, 1.23, which puts it in group 5 of 6, group 1 being the genes least tolerant of losing a copy. Missense variants: 633 observed, 674.29 expected, observed/expected ratio (o/e) 0.94, 90% interval 0.88 to 1. Synonymous variants: 236 observed, 254.18 expected, observed/expected ratio (o/e) 0.93, 90% interval 0.83 to 1.03.
Gene-disease validity (ClinGen):
ClinGen rates the evidence that SERPIND1 causes each of these diseases.
heparin cofactor 2 deficiency (autosomal dominant): Definitive.
Homologues: Orthologues: chimpanzee SERPIND1 (99% identical), macaque SERPIND1 (96% identical), dog SERPIND1 (86% identical), rabbit SERPIND1 (85% identical), guinea pig SERPIND1 (84% identical), rat Serpind1 (82% identical), mouse Serpind1 (82% identical), pig SERPIND1 (77% identical), tropical clawed frog serpind1 (60% identical), zebrafish serpind1 (52% identical). Paralogues in human: SERPINA3 (26% identical), SERPINB1 (26% identical), SERPINA9 (26% identical), SERPINA10 (25% identical), SERPINB9 (25% identical), SERPINC1 (25% identical), SERPINA6 (24% identical), SERPINA1 (24% identical), SERPINB6 (24% identical), SERPINB11 (24% identical), SERPINB8 (24% identical), SERPINA11 (23% identical), and 24 more.
Diseases named in the same sentence as SERPIND1 in open-access papers:
SERPIND1 is named in the same sentence as 73 diseases in open-access papers, as found by Europe PMC text mining. Sharing a sentence is not in itself a finding about the gene and the disease. The quoted sentences say what the papers report.
thrombosis (8 papers, 2013 to 2025). "Defects in SERPIND1, leading to HCII deficiency are the cause of thrombophilia, a haemostatic disorder characterized by a tendency to recurrent thrombosis, causing a hypercoagulation state (Tollefsen, Pestka & Monafo, 1983)." (PMID 26557426, 2015). "Coagulation-related factors, such as F2, SERPIND1, SERPINF2, SERPINA3, FGA, FGB, and FGG, are also downregulated, leading to coagulation dysfunction in the body, which is not conducive to post-exercise recovery and can even lead to thrombosis in severe cases." (PMID 40646880, 2025).
atherosclerosis (7 papers, 2018 to 2023). A disease characterized by the build-up of fatty material and calcium deposition in the arterial wall resulting in partial or complete occlusion of the arterial lumen. "SerpinD1 (heparin cofactor II) is a serine protease inhibitor that has been reported to be protective against atherosclerosis in human and mouse studies, and levels were reported in one study to be decreased in RA synovial fluids compared to healthy controls." (PMID 37899440, 2023). "Serpin peptidase inhibitor D (SERPIND1, heparin cofactor II) levels have been associated with in-stent restenosis of peripheral arteries, and the staining for SERPIND1 in human coronary lesions was correlated with the degree of atherosclerosis in the PDAY study." (PMID 34479557, 2021).
ovarian carcinoma (7 papers, 2018 to 2024). A malignant neoplasm originating from the surface ovarian epithelium. "Specifically, SERPIND1 has been implicated in promoting the development of ovarian cancer by augmenting the phosphorylation of the PI3K/AKT pathway." (PMID 38671425, 2024). "The results showed that FIGO stage and SERPIND1 expression were risk factors of prognosis of epithelial ovarian cancers." (PMID 31637210, 2019). "We found that FIGO stage and SERPIND1 expression were independent risk factors of prognosis of epithelial ovarian cancers." (PMID 31637210, 2019). "Our results ultimately showed that SERPIND1 could be an effective early diagnostic and prognostic marker for epithelial ovarian cancers and potentially serve as a novel drug target." (PMID 31637210, 2019). "In addition, our data showed that SERPIND1 overexpression was associated with shorter disease-free survival rates and shorter overall survival times in ovarian cancer patients." (PMID 31637210, 2019). "While these data strongly suggest a connection between HE4 and SERPIND1, which may be related to their roles in promoting ovarian cancer metastasis, further study of the association between these two proteins is required." (PMID 29740539, 2018). "The SERPIND1 protein, which belongs to a family of serine protease inhibitors and is highly expressed in ovarian cancer tissues, confers poor prognoses in ovarian cancer." (PMID 35740424, 2022). "Other soluble ECM proteins, such as vitronectin (the 11th), SERPIND1 (the 38th), and periostin (the 112th), also exhibit different oncogenic activities in ovarian cancer." (PMID 35740424, 2022). "This studied aimed to investigate the expression and clinical significance of SERPIND1 in epithelial ovarian cancer, as well as its effect on the malignant biological behavior of ovarian cancer cells and the related regulatory mechanisms." (PMID 31637210, 2019). "This present study aimed to examine the expression of SERPIND1 in epithelial ovarian cancers and further analyze its relationship with clinicopathological parameters." (PMID 31637210, 2019). "In this study, the ovarian cancer cell line ES-2 that had low SERPIND1 expression was selected as the experimental cell line for the overexpression of the SERPIND1 gene." (PMID 31637210, 2019). "The strongly positive expression rate of SERPIND1 was significantly higher in FIGO stage III–IV epithelial ovarian cancers than in stage I–II epithelial ovarian cancers (85.1% vs. 43.5%, P < 0.01)." (PMID 31637210, 2019). "The results showed that after the overexpression of the SERPIND1 gene, the proportion of S-phase cells was higher in ovarian cancer cells than in the control groups." (PMID 31637210, 2019). "Meanwhile, the inhibition of SERPIND1 expression in ovarian cancer cells resulted in opposite effects." (PMID 31637210, 2019). "We examined SERPIND1 expression in four human ovarian cancer cell lines (CAOV3, OVCAR3, SKOV3, and ES-2) and found that SERPIND1 was expressed in all human ovarian cancer cell lines, with lower expression in ES-2 and higher expression in CAOV3 and OVCAR3." (PMID 31637210, 2019). "To further analyze the role of SERPIND1 in ovarian cancer cells, we examined the major proteins of epithelial–mesenchymal transition (EMT), including MMP2, MMP9, Vimentin, N-cadherin, and E-cadherin." (PMID 31637210, 2019). "We also analyzed the relationship between SERPIND1 expression and progression-free survival in epithelial ovarian cancer." (PMID 31637210, 2019). "We analyzed the data of the 113 patients with primary epithelial ovarian cancers and compared the clinicopathological parameters with SERPIND1 tissue expression." (PMID 31637210, 2019). "The results showed that SERPIND1 was expressed in all four human ovarian cancer cell lines, with lower expression in ES-2 and higher expression in CAOV3 and OVCAR3." (PMID 31637210, 2019).
ovarian carcinoma (continued). "At day 26 after ovarian cancer cell implantation, the average tumor weight in the SERPIND1 overexpression group was ~2.80 times that of the control group." (PMID 31637210, 2019). "The study also investigated the effect of SERPIND1 on the malignant biological behavior of ovarian cancer cells and the related regulatory mechanisms." (PMID 31637210, 2019). "In conclusion, we found that SERPIND1 was overexpressed in epithelial ovarian cancer, and such overexpression predicted a poor prognosis of the disease." (PMID 31637210, 2019). "The scratch-wound assay and Transwell experiments were used to study the effects of SERPIND1 on the migration and invasion of ovarian cancer cells." (PMID 31637210, 2019). "Our findings revealed that SERPIND1 was highly expressed in epithelial ovarian cancers, and the expression increased with increase in the degree of malignancy." (PMID 31637210, 2019). "The effect of SERPIND1 on the proliferation of ovarian cancer cells was studied using the MTT assay." (PMID 31637210, 2019). "In contrast, the inhibition of SERPIND1 expression in ovarian cancer cells reduced the phosphorylation of PI3K/AKT, increased E-cadherin expression, and reduced the expressions of N-cadherin, Vimentin, MMP2, and MMP9." (PMID 31637210, 2019). "We examined cell-cycle changes before and after the differential expression of SERPIND1 in ovarian cancer cells." (PMID 31637210, 2019). "SERPIND1 promoted the proliferation, migration, invasion, G1-to-S phase transition, and epithelial–mesenchymal transition of ovarian cancer cells and inhibited their apoptosis by promoting phosphorylation in the phosphoinositide 3-kinase/protein kinase B (PI3K/AKT) pathway." (PMID 31637210, 2019). "However, the role of SERPIND1 in the development of epithelial ovarian cancer remains poorly understood." (PMID 31637210, 2019). "The addition of the PI3K/AKT pathway inhibitor LY294002 to SERPIND1-overexpressing cells could reverse the promoting effect of SERPIND1 on the malignant biological behavior of ovarian cancer cells." (PMID 31637210, 2019). "We also examined SERPIND1 expression in four human ovarian cancer cell lines: CAOV3 (human ovarian adenocarcinoma cells), OVCAR3 (human ovarian adenocarcinoma cells), ES-2 (human ovarian clear-cell carcinoma cells), and SKOV3 (human serous ovarian cancer cells)." (PMID 31637210, 2019). "Based on these results, we speculated that SERPIND1 regulated the cell migration, invasion, proliferation, apoptosis, and cell cycle of ovarian cancer cells via the PI3K/AKT pathway." (PMID 31637210, 2019). "This study illustrated the effects of SERPIND1 on the malignant biological behavior of ovarian cancer cells, and showed that NF-κB1 regulated SERPIND1, which subsequently mediated cell migration, invasion, proliferation, apoptosis, cell cycle regulation, and EMT via the PI3K/AKT signaling pathway." (PMID 31637210, 2019). "In conclusion, our results indicated that SERPIND1 could be an effective marker for assessing the prognosis of ovarian cancer." (PMID 31637210, 2019). "Based on these results, we speculate that SERPIND1 regulated the EMT of ovarian cancer cells via the PI3K/AKT pathway." (PMID 31637210, 2019). "We found that SERPIND1 expression was significantly elevated in epithelial ovarian cancer." (PMID 31637210, 2019). "Patients with higher expression of SERPIND1 in ovarian cancer tissues had poor prognoses." (PMID 31637210, 2019). "With the experiments in vivo, we found that SERPIND1 could promote the ability of ovarian cancer cells for proliferation and migration." (PMID 31637210, 2019). "By elucidating its mechanism underlying the promotion of malignant biological behavior of ovarian cancer by SERPIND1, we demonstrated that SERPIND1 could potentially serve as a novel drug target." (PMID 31637210, 2019).
ovarian carcinoma (continued). "The ovarian cancer cell lines CAOV3 and OVCAR3 that had higher SERPIND1 expression was selected as the experimental cell lines for the suppression expression of the SERPIND1 gene." (PMID 31637210, 2019). "Thus, SERPIND1 may serve as a potential target for ovarian cancer therapy." (PMID 31637210, 2019). "However, some researches had identified that SERPIND1 was upregulated in non small cell lung cancer (NSCLC), ovarian cancer and leukemia." (PMID 38355782, 2024). "Based on these results, we speculate that SERPIND1 promoted the proliferation, migration, invasion, G1-to-S phase transition, and EMT of ovarian cancer cells as well as inhibited their apoptosis via the PI3K/AKT pathway." (PMID 31637210, 2019). "In addition, they found that 37/50 ovarian cancer samples showed positive expression of both SERPIND1 and HE4, and Spearman correlation analysis confirmed that HE4 and SERPIND1 were positively correlated." (PMID 29740539, 2018). "In addition, the transcription factor NF-κB1 could bind to the promoter region of SERPIND1 and regulate SERPIND1 expression, which in turn could affect the PI3K/AKT pathway and promote the malignant biological behavior of ovarian cancer cells." (PMID 31637210, 2019).
COVID-19 (6 papers, 2021 to 2024). A disease caused by infection with severe acute respiratory syndrome coronavirus 2. "The regulation of SerpinD1 in COVID-19 is controversial, as a study has shown that SerpinD1 was higher in moderate and severe cases." (PMID 38760690, 2024). "The predicted network showed F2, ACE, REN, and SERPIND1 as some of the interacting partners with LPARs and serving as a crucial connecting node between the receptor and the studied diseases (AD, DM, and COVID-19)." (PMID 38383841, 2024). "Conversely, components of the coagulation cascade (SERPINA5, SERPIND1, PROC, CPB2, F13B, and KLKB1) and proteins involved in cholesterol metabolism were downregulated with the severity of COVID-19 but increased over time." (PMID 35958562, 2022). "Here, we selected five significant proteins for COVID-19 non-severe versus severe comparison: heparin cofactor 2 (SERPIND1), thyroxine-binding globulin (SERPINA7), angiotensinogen (AGT), carbonic anhydrase-1 (CA1), and carbonic anhydrase-2 (CA2) for docking study." (PMID 33995121, 2021). "Further, the deep plasma proteome study of non-severe versus severe COVID-19 patients revealed only 38 differentially expressed proteins, out of which proteins such as FGG, S100A8, VWF, SAA4, SERPIND1, and SERPINA6 were identified to be significantly upregulated in the COVID-19 severe patients." (PMID 33995121, 2021).
depression (4 papers, 2020 to 2024). "The analysis of plasma proteins in patients indicates that one of the candidate diagnostic biomarkers of depression may be the SERPIND1 protein, which is upregulated in depressed patients." (PMID 39062058, 2024). "Consistently, Serpind1 is considered a candidate gene for depression." (PMID 33552119, 2020).
lung carcinoma (4 papers, 2019 to 2022). "Hereinto, SERPIND1 acts as a potential oncogene in the development of tumor, including in lung cancer." (PMID 32596344, 2020).
breast carcinoma (3 papers, 2016 to 2025). "A recent study also implicated Serpins, including SERPIND1, in metastasis of breast cancer to the brain." (PMID 27776348, 2016). "Elevated levels of SERPIND1 are found in hepatocellular carcinoma, multiple myeloma, breast cancer, colorectal tumors, and other cancers." (PMID 35163468, 2022).
acute myocardial infarction (2 papers, 2018 to 2025). Necrosis of the myocardium, as a result of interruption of the blood supply to the area. "In a follow-up investigation of 110 patients with acute myocardial infarction, elevated expression of Serpind1 was found to reduce the risk of atherosclerotic thrombosis." (PMID 40422915, 2025).
autism (2 papers, 2019 to 2021). Persistent deficits in social interaction and communication and interaction as well as a markedly restricted repertoire of activity and interest as well as repetitive patterns of behavior. "Besides, three proteins i.e., A2M, SERPINA1, and SERPIND1 were also associated with complement and coagulation cascades in the present study, indicating that complement system and coagulation cascades may be involved in the pathogenesis of autism." (PMID 30941018, 2019).
non-small cell lung carcinoma (2 papers, 2019 to 2022). A group of at least three distinct histological types of lung cancer, including non-small cell squamous cell carcinoma, adenocarcinoma, and large cell carcinoma. "In non-small-cell lung cancer (NSCLC) patients, increased SERPIND1 expression was associated with shorter overall survival rates, suggesting that SERPIND1 may be a target gene of BRAF V600E." (PMID 35163468, 2022).
Sepsis (2 papers, 2020 to 2021). Sepsis is defined as life-threatening organ dysfunction caused by a dysregulated host response to infection. "For example, we observed a significant increase in genes encoding F2rl2, F5, Thbs1, Serpind1 in lung PCV, suggesting that both PCV and capEC are important for coagulation cascade activation in sepsis." (PMID 34638535, 2021).
acute lymphoblastic leukemia (1 paper, 2019). Leukemia with an acute onset, characterized by the presence of lymphoblasts in the bone marrow and the peripheral blood. "Another study found that SERPIND1 expression is upregulated in acute lymphoblastic leukemia, and SERPIND1 may be a candidate cancer biomarker for diagnosing the disease." (PMID 31637210, 2019).
B-cell acute lymphoblastic leukemia (1 paper, 2019). A neoplasm of lymphoblasts committed to the B-cell lineage, typically composed of small to medium-sized blast cells. "High-level serum SERPIND1 expression was observed in patients with B-cell acute lymphoblastic leukemia." (PMID 31040200, 2019).
breast tumors (1 paper, 2021). "In addition, some of the DEPs identified in these signaling pathways were also differentially expressed between the male and female breast tumors, such as the ones encoded by CES1, CRYAB, NSF, PRKDC and SERPIND1 genes." (PMID 33656060, 2021).
cervical cancer (1 paper, 2019). A primary or metastatic malignant neoplasm involving the cervix. "Western blot was used to examine SERPIND1 expression in ovarian tissues in 27, 24, 8, and 9 cases of malignant, borderline, benign, and normal ovarian tissues (normal ovarian specimens resected during surgery for cervical cancer), respectively." (PMID 31637210, 2019).
clear-cell carcinomas (1 paper, 2019). "Positive and strongly positive rates of SERPIND1 expression were reported for the malignant group (90.40 and 67.20%, respectively), the malignant group included 77 serous carcinomas, 18 mucinous carcinomas, 8 endometrioid carcinomas, and 10 clear-cell carcinomas." (PMID 31637210, 2019).
epithelial ovarian tumors (1 paper, 2019). "Relationships between the positive rate of SERPIND1 expression and clinicopathological characteristics of patients with malignant epithelial ovarian tumors." (PMID 31637210, 2019).